VIM (vimentin)
Diseases named in the same sentence as VIM in open-access papers (continued):
Sharing a sentence is not in itself a finding about the gene and the disease.
lymph node metastasis (continued). "Univariate analysis showed significant relationships between the Overall survival (OS) and higher T stage, high expression of CDK5, MiR-21, N-cadherin, Vimentin, low expression of E-cadherin, and lymph node metastasis (p < 0.05)." (PMID 26690371, 2015). "Meanwhile, p120ctn cytoplasmic expression negatively correlated with E-cadherin expression (P<0.001) and positively correlated with vimentin expression and lymph node metastasis (P<0.05)." (PMID 24505377, 2014). "In particular, AQP3 and E-cadherin were associated with lymph node metastasis, while AQP3 and vimentin were associated with Lauren classification, and E-cadherin was associated with depth of tumor invasion." (PMID 24887009, 2014). "Vimentin was also reported to be highly expressed in CRC, and high expression of vimentin was found to be associated with lymph node metastasis and disease recurrence in CRC." (PMID 24555885, 2014). "Furthermore, vimentin expression independently predicted lymph node metastases after adjusting for age and curettage histology in a multivariate analysis with an HR of 1.83 (95% CI 1.13–2.95, P = 0.014)." (PMID 39516342, 2024). "We assessed whether vimentin expression in preoperative biopsies predicts poor prognosis and lymph node metastasis in a large multicentre cohort." (PMID 39516342, 2024). "However, we found that the expression of vimentin was positively correlated with gender, depth of invasion, clinical stage, lymph node metastasis, and vascular invasion (p < 0.05)." (PMID 31186031, 2019). "Moreover, upregulated vimentin is related to lymph node metastasis (OR: 2.288, 95%CI: 1.159-4.517), TNM stages (OR: 1.957, 95%CI: 1.333-2.873), and N stage (OR: 2.316, 95%CI: 1.482-3.620)." (PMID 29955607, 2018). "Additionally, upregulated vimentin was related to lymph node metastasis, advanced TNM stages, and N stage." (PMID 29955607, 2018). "Similarly, Vimentin expression was significantly increased in samples connected with a higher grade of cell differentiation (p = 0.006) and with lymph node metastasis (p = 0.039)." (PMID 28570699, 2017). "Moreover, high Vimentin expression was only significantly correlated with lymph node metastasis (p = 0.031)." (PMID 28570699, 2017). "Correlation between E-cadherin, vimentin and lymph node metastasis and p120ctn." (PMID 24505377, 2014). "Furthermore, we found that the prognostic power of vimentin expression was better than that of lymph node metastasis." (PMID 17325702, 2007). "However, up-regulated vimentin expression was associated with several clinicopathological factors, including histology of squamous cell carcinoma, smoking, poor differentiation, advanced TNM stages, vascular invasion, lymph node metastasis and recurrence in NSCLC." (PMID 27657690, 2016). "Additionally, in samples derived from patients with lymph node metastasis, higher BMP2 expression levels correlated with higher expression levels of the mesenchymal marker vimentin." (PMID 36175474, 2022). "MACC1, vimentin, and E-cadherin protein levels in NPC tissues were significantly correlated with T stage (p=0.011), N stage (which is synonymous with lymph node metastasis; p=0.013, 0.011, 0.001, respectively), and cancer stages I to IV (p=0.023, 0.037, 0.022, respectively)." (PMID 33854976, 2021). "Of notion, vimentin protein expression (IHC score) is significantly higher in patients with lymph node metastases (n = 30) than in patients without lymph node metastasis (n = 55)." (PMID 27966589, 2016). "Importantly, in patients with HNSCC, vimentin expression was significantly higher in those having lymph node metastases than in those without lymph node metastasis, as shown by IHC staining." (PMID 38611032, 2024). "Negative vimentin expression in EC correlated significantly with lymph node metastasis, deep myometrium invasion (MI), lymph vascular space invasion (LVSI), advanced Federation International of Gynecology and Obstetrics Association (FIGO) stages (III and IV), and high tumor grade." (PMID 35320951, 2022).
lymph node metastasis (continued). "When we further analysed the survival data for stage II (without lymph node metastasis) and stage III (with lymph node metastasis) CRC, we found that irrespective of the lymph node status, vimentin expression was significantly associated with a higher disease recurrence rate." (PMID 17325702, 2007). "Additionally, high Vimentin expression was associated with poor DFS in patients with early pathological stage disease (I-II; AHR = 1.86; 95% CI = 1.13–3.08; p = 0.016, S5 Table) and in patients without lymph node metastasis (N0; AHR = 1.79; 95% CI = 1.11–2.88; p = 0.017, S5 Table)." (PMID 28570699, 2017). "Moreover, a transcriptomic study comparing HN12, an OSCC cell line derived from lymph node metastasis, to HN4, its non-metastatic equivalent, showed an 87-fold increase in vimentin expression." (PMID 35207438, 2022).
renal fibrosis (57 papers, 2014 to 2025). A final common manifestation of a wide variety of chronic kidney diseases characterized by glomerulosclerosis and tubulointerstitial fibrosis. "Under a high glucose environment, C-peptide significantly reduces EMT and renal fibrosis by reducing the expression of Snail, Vimentin, α-SMA, and CTGF." (PMID 40822939, 2025). "In a rat model of renal fibrosis induced by renal allograft transplantation, the antifibrotic effect of pirfenidone was demonstrated by a decrease in vimentin expression after pirfenidone administration." (PMID 39133399, 2024). "After the overexpression of Snail, the antifibrotic effect of β-Mag was neutralized, indicating that β-Mag inhibited renal fibrosis by decreasing the expression of Snail and Vimentin." (PMID 39451219, 2024). "The development of renal fibrosis was assessed by the detection of Vimentin (VIM), α-smooth muscle actin (α-SMA) and collagen by immunohistochemistry and Sirius Red staining, respectively." (PMID 39202772, 2024). "And, knockout of ISG15 led to decreased TGFβR1 and its downstream p-Smad2 levels, reduces transcription levels of fibrotic genes such as α-SMA, Fn1, and Vimentin, ultimately inhibited renal fibrosis." (PMID 39113797, 2024). "In conclusion, based on the in vivo and in vitro experiments, β-Mag retards the EMT and renal fibrosis by regulating the TGF-β/JNK/Smad2-mediated Snail/Vimentin axis." (PMID 39451219, 2024). "In summary, β-Mag hampered renal fibrosis through the inhibition of the JNK/Smad2-mediated Snail/Vimentin axis." (PMID 39451219, 2024). "Compared with Con mice, the indicators related to renal fibrosis and endothelial-to-mesenchymal transition (EndMT) like collagen IV, vimentin and fibronectin were significantly increased in the DKD group, but decreased in the En group." (PMID 36589853, 2022). "To verify the extent of renal fibrosis remission, we assessed the intrarenal collagen accumulation by Masson staining and the expression of fibrosis-related proteins including vimentin and α-SMA in diabetic-induced renal tissues by immunofluorescence staining." (PMID 36544775, 2022). "We further verified that compared with DKD group, Sac/Val reduced the expression of vimentin, collagen IV, and fibronectin, which were marker proteins of EndMT and renal fibrosis." (PMID 36589853, 2022). "α-SMA, TGF-β, and Vimentin are fibrosis marker proteins whose expression is positively correlated with the degree of renal fibrosis." (PMID 36160409, 2022). "Vimentin participates in EMT and also exhibits increased levels in the kidney in DKD patients, causing EMT-related renal fibrosis." (PMID 36277688, 2022). "We observed that SMM improved histopathological changes in renal fibrosis, downregulated the expression of vimentin, collagen 3, fibronectin and α-SMA, and upregulated the expression of E-cadherin." (PMID 36271349, 2022). "The present study revealed that FG-4592 pretreatment decreased the expression of collagen IV, fibronectin, and vimentin, the parameters representing the level of renal fibrosis." (PMID 32051732, 2020). "The increases of serum BUN, Scr, renal fibrosis-related genes and proteins (Vimentin, α-SMA, and TGF-β1), and autophagy-related genes and proteins, (ATG5 and LC3II) were inhibited in TLR4−/− mice." (PMID 32108135, 2020). "We also investigated the expression of proteins related to renal fibrosis, such as E-cadherin, vimentin, α-SMA, fibronectin and collagen I in PBS- or rhALR-treated rat UUO kidneys." (PMID 24844766, 2014). "The Western blotting results verified the protein expression of α-SMA and vimentin, which proved that HKC could ameliorate renal fibrosis injury and renal tubular epithelial injury caused by HG in HK-2 cells in vitro." (PMID 40371325, 2025).
renal fibrosis (continued). "In patients with LN and other CKDs, such as IgAN, minimal change disease, hypertensive nephropathy, and DN, elevated urinary vimentin mRNA levels correlate with increased proteinuria, renal fibrosis scores, and a decrease in GFR, highlighting its potential as a diagnostic marker for renal outcomes." (PMID 40141260, 2025). "Thus, we detected the expressions of α-SMA, Vimentin and Collagen I to measure the degree of renal fibrosis." (PMID 39736520, 2024). "However, how the transcription factor Snail regulates transcriptional activity and its direct or indirect binding to the Vimentin promoter in renal fibrosis remains to be further studied." (PMID 39451219, 2024). "N-cadherin, α-SMA, Vimentin, and collagen are key factors contributing to renal fibrosis." (PMID 39382800, 2024). "In addition, the qRT-PCR results demonstrated increases in two renal fibrosis markers, i.e., vimentin and FSP-1, in the SAMP1-50wk group plus a decrease in the expression of podocin (a glomerulosclerosis marker) in these mice." (PMID 38132237, 2023). "Furthermore, in the UUO mice model of renal fibrosis, Sch B markedly decreases the expression of collagen IV and vimentin in the kidney, and the levels of pro-fibrotic transcription factors, including Slug and Zeb2, are also reduced." (PMID 38067580, 2023). "The high expressions of TGF-β, Twist1 (transcription factor inducing EMT) and vimentin (fibroblast marker) in UUO rats further suggested that EMT may be one of the important mechanisms of UUO-induced renal fibrosis." (PMID 35408745, 2022). "Compared with DKD mice, Sac/Val treatment could decrease the expression of indicators related to EndMT and renal fibrosis like vimentin, collagen IV and fibronectin in kidney." (PMID 36589853, 2022). "Moreover, the expression levels of markers for renal fibrosis, such as vimentin, α-SMA, and Col I decreased." (PMID 33729484, 2021). "Alpha-actinin-1 and Moesin detected after 1 week of UUO may be used as potential biomarkers of tubular injury, whereas Annexin A1, Clusterin and Vimentin may be the candidate markers of renal fibrosis." (PMID 25791774, 2015). "Our study showed that upon the administration of rhALR, the expression of proteins related to renal fibrosis, such as vimentin, α-SMA, collagen I and fibronectin, were reduced in obstructed kidney, whereas epithelial marker proteins, such as E-cadherin, was increased in obstructed kidney." (PMID 24844766, 2014). "However, the expression of ECM genes such as mesenchymal collagens Col3a1 and Col1a1 as well as EMT markers found in tumorigenic EMT or renal fibrosis, including EMT-associated cytoskeleton Vimentin, Fn1 and Sparc, were significantly increased in Smarca4cKO tubular cells." (PMID 37727504, 2023). "Therefore, the reduced expression of α-SMA and Vimentin in the ADR-induced FSGS model by the YSHS granule further suggested that the YSHS granule may prevent the progress of renal fibrosis in ADR-induced FSGS through the inhibition of EMT." (PMID 35784691, 2022). "We also demonstrated that renal fibrosis was attenuated by PRDM16 overexpression, as the mRNA levels of Col1a1, Col3a, Fibronectin, and Vimentin, the protein levels of Fibronectin and α-SMA, and collagen deposition decreased." (PMID 40758676, 2025). "In the kidneys of Prdx5 KO mice, the expression of renal fibrosis markers, such as SMA, vimentin, FN, TGF-β, and CTGF, was already slightly increased compared to Prdx5 WT." (PMID 39857434, 2025). "To further validate the effect of SPDEF on renal fibrosis, we tested the expression of renal fibrosis related indicators α-SMA and Vimentin." (PMID 39736520, 2024). "Immunohistochemical staining for fibrotic components showed lower levels of FN1, vimentin, and α-SMA in the kidneys of MΦ atg5−/− mice than in those of WT littermate mice, indicating reduced severity of renal fibrosis." (PMID 38594728, 2024).
renal fibrosis (continued). "HDHW down-regulated the levels of fibrosis marker proteins, including α-smooth muscle actin (α-SMA), vimentin, and transforming growth factors–β(TGF-β), which in turn reduced renal fibrosis." (PMID 36160409, 2022). "RTT extract significantly ameliorated renal injury and renal fibrosis in the renal tissue of STZ-induced diabetic mice as demonstrated by the decreased expression level of Fibronectin (65%), Vimentin and α-SMA (75% & 53%)." (PMID 35142600, 2022). "In the present study, CeNP-PEG treatment significantly ameliorated renal fibrosis by increased E-cadherin protein expression, and decreased α-SMA, Vimentin and Fibronectin expression both in vitro and in vivo." (PMID 34983531, 2022). "To assess the effect of HDHW on renal fibrosis, we performed Masson staining and immunohistochemical staining for α-SMA, TGF-β, and Vimentin of rat kidney tissues, and further detected the level of α-SMA by Western blot." (PMID 36160409, 2022). "The qRT-PCR analysis confirmed further increases in the renal fibrosis markers FSP-1 and vimentin in the SAMP1-50wk mice, and that the expression of the glomerulosclerosis marker podocin was decreased in the SAMP1-50wk mice." (PMID 35646947, 2022). "Knock down of RAGE ameliorated renal fibrosis by TGF-β1 treatment, the expression of vimentin, Collagen I&III, and fibronectin are decreased." (PMID 35461309, 2022). "Firstly, we used vimentin and α-SMA as mesenchymal markers of pathological changes in renal fibrosis in DKD." (PMID 36294921, 2022). "The gene and protein expression levels of profibrosis factors such as TGF-β1, CTGF, and VIM were detected by fluorescence quantitative PCR and Western Blot, which were consistent with the characteristics of the progression of DKD to renal fibrosis." (PMID 35186975, 2021). "Silencing NEAT1 in HK2 cells resulted in inhibition of the EMT-related markers alpha smooth muscle actin (α-SMA) and vimentin (VIM) and the renal fibrosis-related markers transforming growth factor-β1 (TGF-β1) and connective tissue growth factor (CTGF)." (PMID 32054986, 2020). "Renal fibrosis-related proteins and genes (TGF-β1, Vimentin, and α-SMA) were measured via immunohistochemical staining of α-SMA, real-time PCR, and western blotting." (PMID 32108135, 2020). "For example, upregulation of DEPs VIM, IQGAP1, and moesin is closely related to EMT and renal fibrosis, and GSN, another DEP, is related to renal tubule epithelial cell apoptosis." (PMID 27036204, 2016). "Therefore, Vimentin may be a potential urinary marker for renal fibrosis." (PMID 25791774, 2015). "FSP-1 and vimentin represent additional markers of renal fibrosis, but their expression profiles have not been systematically examined in LN." (PMID 40141260, 2025). "Our study found that under chronic hypoxia, mitophagy activation effectively inhibited the expression of Vimentin, α-SMA, Collagen I, and FN1, suggesting that mitophagy may play a protective role in EMT progression and renal fibrosis." (PMID 40305351, 2025). "By detecting the levels of the fibrosis-related proteins SMA, ECA, TGF-β, and VIMENTIN, as well as the renal tubular injury–related factors AKLOTHO and EDN1, our results reveal that the extent of renal fibrosis and tubular injury in the WTDI/R mice was more severe than in the KODI/R mice." (PMID 39656542, 2024). "Similarly, 14 days after UUO, the kidneys of MΦ atg5−/− mice revealed less renal fibrosis, as indicated using quantitative SR and Masson staining, and reduced staining for fibrotic components (FN1, vimentin, and α-SMA) compared to WT littermate mice." (PMID 38594728, 2024). "Fibroblast-to-myofibroblast transition, a representative process among several routes of exaggerated ECM accumulation in renal fibrosis, is characterized by the expression of mesenchymal cell products such as α-SMA, vimentin (intermediate filament), and collagen I." (PMID 34588982, 2021). "Next, renal fibrosis markers were assessed, including COL1A1, VIM, CDH1, and ACTA2." (PMID 32854194, 2020).
renal fibrosis (continued). "Furthermore, the expression of the renal fibrosis markers TGF-β1 and CTGF, as well as the EMT markers vimentin and α-SMA, was detected by immunohistochemistry and qRT-PCR." (PMID 32054986, 2020). "In contrast, administration of IL-22 significantly downregulated the renal overexpression of Fibronectin, Collagen IV, Vimentin, and α-SMA, suggesting that IL-22 intervention could alleviate renal fibrosis in AAN." (PMID 31616439, 2019). "To unravel the physiological roles of PPM1K in renal fibrosis, we analyzed the RNA-sequencing dataset of a PPM1K-overexpressing HK2 cell line (GSE212681) and identified reduced expression of fibrosis-related genes such as Col1A1, Col2A1, CTGF, vimentin, and FN1 (Fig. EV3)." (PMID 40588562, 2025). "Protein level demonstrated that PCA not only decreased vimentin expression and enhanced E-cadherin expression, but inhibited UUO-induced collagen IV and α-SMA upregulation, indicating that it could mitigate EMT in a rat model of UUO-induced renal fibrosis." (PMID 35758295, 2022). "Moreover, we also confirmed the inhibitory effect of HDHW on renal fibrosis from three indicators, α-SMA, Vimentin, and TGF-β, which we have never observed before." (PMID 36160409, 2022).